MYC (MYC proto-oncogene, bHLH transcription factor)
Diseases named in the same sentence as MYC in open-access papers (continued):
Sharing a sentence is not in itself a finding about the gene and the disease.
tumor (continued). "It is possible that in LMS tumors with high accumulation of DNA damage, disruption of cell cycle checkpoint regulation through RB1, CDKN2A/B, MYC, FBXW7, or NF1 is necessary to maintain the viability of the tumor." (PMID 35468996, 2022). "We clearly observed c-MYC recruitment to the promoter of ABCC1 and ABCC4 in tumours from Eμ-Myc mice compared with controls that correlate with its higher gene expression." (PMID 35326669, 2022). "MYC was shown to have an opposing role in DDR signaling by two distinct pathways—ATM/CHK2 (obstacle for malignant transformation) and ATR/CHK1 (tumor maintenance)." (PMID 35408915, 2022). "As target molecules with critical roles in various cancers, TOPK, c-MYC, and N-MYC were exclusively expressed only in tumor cells." (PMID 36970725, 2022). "At present, preclinical experiments have proved that ixazomib has not only anti-tumor activity in DLBCL cell lines, but also inhibitory activity in DLBCL cell lines that have translocation of MYC and BCL2, and its IC50 value is 40-200 nm." (PMID 35303910, 2022). "One study loaded the MYC gene-targeted CRISPR/Cas9 system into anti-CD19-CARsEVs, which accumulated in CD19-positive tumour cells rapidly and efficiently targeted the MYC oncogene." (PMID 36167539, 2022). "A significant difference in the number of alterations and type of RCAs in MYC+ versus MYC− tumors, represented by a higher GPS value in MYC+ tumor cases, was also documented." (PMID 36051032, 2022). "Genes significantly associated with the outcomes were enriched for early estrogen response pathway, DNA repair pathways as well as targets of transcription factors such as E2F4, MYC, and ETS1 that have recognized roles in tumor characteristics and survival." (PMID 36584096, 2022). "MYC is frequently overexpressed in TNBC16–19 and plays a role in tumor recurrence, metastasis, and chemotherapy response." (PMID 35760778, 2022). "Eight hub genes (CDK1, EGFR, UBC, MYC, CCNB1, RHOB, CDC6, and CDC20) have tumor suppressor functions, while five hub genes (CDK1, EGFR, FYN, UBC, and CCNB1) are protein kinases as well." (PMID 35632527, 2022). "Targeting MYC and NOTCH2 also decreased the capacity for self-renewal and tumor formation corroborating the importance of the MUC1-C→MYC→NOTCH2 pathway in driving the SCLC CSC state." (PMID 35612556, 2022). "In conclusion, upon activation of the MYC/HIF1 pathway, tumor glycolysis is enhanced, tumors require more energy and endogenous polyamine synthesis is reduced." (PMID 35912204, 2022). "Analysis of bulk RNA-seq data on CKI-treated MDA-MB-231 cells displayed that proliferation-related pathways like MYC targets, G2M checkpoint and E2F targets were significantly down-regulated in the CKI-treated tumor cells compared with the control cells." (PMID 36389835, 2022). "Our data demonstrated that PVT1 circular RNA (CircPVT1), MYC, and CASC11 are significantly (p < 0.05) overexpressed in CRC tumor samples compared to normal margin tissues." (PMID 36052265, 2022). "Recent studies have shown that NSD3-induced histone methylation is functionally involved in tumor initiation and progression by facilitating the transactivation of oncogenic signaling, such as NOTCH, MYC, and mTORC1." (PMID 36291782, 2022). "It has been shown that the oncoprotein MYC is the main downstream target of activated WNT signaling and is essential to maintain CRC tumor growth." (PMID 35673898, 2022).
tumor (continued). "For example, activation of MYC can induce the transcription of both CD47 and PD-L1 and thereby suppress the anti-tumor immune response." (PMID 34980132, 2022). "Members of the let-7 family are known tumor suppressors that modulate oncogenes such as HMGA2, MYC and RAS." (PMID 36613487, 2022). "R1R361H and R4wt were derived from a tumor that was described as consensus molecular subtype 2 (CMS2), which is characterized by WNT and MYC activation." (PMID 35805024, 2022). "Compared with the normal tissues, FN1, IL10, and MYC were highly expressed, while the expression of CD247 was decreased in tumor bladder tissues." (PMID 36389789, 2022). "MYC inhibition has been demonstrated to inhibit ATRT tumor growth in vivo and in vitro, particularly in the ATRT–MYC subgroup." (PMID 35892904, 2022). "Mechanistically, L-DON and JHU-083 suppressed tumor glutamine metabolism by inhibiting all the glutamine-utilizing enzymes, and simultaneously suppressed tumor glycolysis by activating AMP Kinase (AMPK) and inhibiting the expression of c-MYC." (PMID 35897036, 2022). "Finally, we asked whether the switch in gene expression in MET tumours following MYC overexpression occurs in other murine models in which HCC is triggered by hydrodynamic co-injection of plasmids driving expression of MYC in combination with different known oncogenes (GSE148379)." (PMID 36433941, 2022). "GEGFR, CD40, SPATA2, ZBP1, ID1, and MYC showed a significant CNV amplification in most tumour types; however, TLR3, PDHB, FAS, and MAP3K showed a significant CNV deletion in most tumour types." (PMID 36186436, 2022). "Our findings reveal that NF-κB- and MYC-signaling are both present in CD44+/CD133+/Nestin+ GSCs, with MYChigh GSCs being located in the tumor spheres while NF-κB-RELAhigh GSCs were outgrowing." (PMID 36361720, 2022). "Tumor tissues expressed significantly higher levels of WT1, HIF-1α, B-FGF, and c-MYC and significantly lower levels of SLC22A18 relative to autologous renal tissue." (PMID 36818371, 2022). "It is important to consider that c-MYC-MIZ-1 binding is critical for the development of MBGroup3, modulating the expression of specific genes that maintain the identity of these tumours and distinguish them from other MB subgroups." (PMID 34302498, 2021). "This also revealed that a significant set of LP-184 associated genes are MYC-dependent, which is of interest given the role of MYC in general- and NSCLC-tumor progression." (PMID 33889302, 2021). "Let-7b-5p is an established tumor suppressor in MM, which acts by targeting and downregulating, the receptor of insulin-like growth factor (IGF1R) and the oncogene MYC." (PMID 34359778, 2021). "We found that CYP7A1, GINS2, and PDLIM3 were significantly up-regulated, and MYC, MAMDC4, ADAMTS1, THBS1, and RASD1 were significantly down-regulated in HCC tumor samples compared with normal samples using the TCGA dataset." (PMID 34777484, 2021). "Multiple cancer-related pathways up-regulate SLC2A1 in tumor cells, including HIF1, MYC, PI3K-Akt, and RAS-MAPK." (PMID 33810575, 2021). "Another important tumor suppressor gene showing increased expression after Msi1 silencing is NDRG2, an n-MYC target gene, which is highly expressed in normal tissues, but undetectable in many tumors." (PMID 35011618, 2021). "The rapid tumor growth and aggressive invasion were ascribed to the AFF4/NF-κB/MYC pathway induced by METTL3, while self-renewal maintenance of BC stem cells was performed by the METTL3-AFF4-SOX2 axis." (PMID 33879256, 2021). "Kon and colleagues revealed a novel tumour-suppressor role for CMA in MEF cells, where CMA inhibited the oncogenic activity of MYC by promoting its proteasomal degradation." (PMID 34445233, 2021).
tumor (continued). "Overall, this study provides an in-depth analysis of RRM2B alterations in multiple tumor types, majorly reflected as RRM2B amplifications in conjunction with MYC, and other genes on chromosome 8." (PMID 33868369, 2021). "This work reveals how MYC executes a core arm of its pro-tumorigenic gene expression changes, defines HCF-1 as a tumor-critical MYC co-factor, and provides proof-of-concept for a new way to inhibit MYC in the clinic." (PMID 33416496, 2021). "NSUN2 has been identified as an MYC target correlated to the MYC-dependent proliferation in tumors, and DNMT2 is highly expressed in various tumor tissue cells, implying that DNMT2 functions an oncogenic role in tumorigenesis." (PMID 34272618, 2021). "Usp28 downregulation by shRNA resulted in a significant reduction in c-MYC, c-JUN, and Δp63 protein levels in LSCC primary tumour cells and reduced LSCC cell growth." (PMID 34636321, 2021). "Higher c-MYC and CXCR4 expression was detected in polyp and tumor swab samples compare to normal, whereas expression of CD26 showed in CRC samples is reduced, in comparison to normal and polyp samples." (PMID 34335790, 2021). "Next, correlation analysis indicated that expression of c-MYC and KRT6A, LSD1, G6PD were positively correlated in NSCLC tumor tissues." (PMID 34235156, 2021). "Functional genomic studies have shown the transactivation of MYC through miR-17-92 cluster, both of which result in DLBCL progression by silencing tumor suppressor genes." (PMID 34679437, 2021). "Immunofluorescence staining performed on three of the tissue samples showed co-expression of OCT4 and c-MYC with NANOG, SOX2 and KLF4 by tumor gland cells, and expression of OCT4 and c-MYC exclusively by cells within the stroma." (PMID 34685477, 2021). "In sum, MYC not only integrates KRAS-driven cellular signaling, but reciprocally controls communication with the TME to orchestrate the overall tumor biology." (PMID 34637026, 2021). "RSV did not significantly affect the expression of c-MYC in PE/CA-PJ49 tumor cells, but it resulted in a significant reduction of c-MYC expression in FaDu tumor cells compared to the control (p < 0.002, **) or to PE/CA-PJ49 tumor cells (p < 0.025, *)." (PMID 34204834, 2021). "As part of the MYC/MAX/MXD1 network, MXD1 and MYC compete for binding to MAX, so enhanced MXD1 expression suppresses tumor growth, consistent with our finding here." (PMID 34830961, 2021). "For example, c-MYC has been shown to alter immune cells metabolism and the cancer microenvironment by supporting the expression of HIF-1 and secretion of VEGF in tumour cells." (PMID 34847775, 2021). "The literature expression profile of MYC in clinical tumor and normal samples was conducted via the UALCAN database analysis tool, which highlighted the clinical significance of MYC across various cancers." (PMID 34069906, 2021). "The PTEN tumor-suppressor genes and the AKT, RAS, or MYC oncogenes have also been found to play a role in autophagy and tumor formation." (PMID 34943908, 2021). "Surprisingly, clusters with the strongest oncogenic and tumour suppressor potential share five regulatory regions (MAX, ERG, EP300, AR and MYC)." (PMID 34198662, 2021). "Meanwhile, MTHFD2 promotes PD-L1-mediated tumor immunoresistance through the folate cycle-HBP metabolic pathway and the UDP-GlcNAc-O-GlcNAcylation-MYC-PD-L1 signaling pathway." (PMID 33782411, 2021).
tumor (continued). "Integrative analysis of multiomics data identified EGFR, JUN, MYC, FN1 and SERPINE1 as key modulators of the tumour immune microenvironment and potential targets for combination therapies which was validated in two validation sets." (PMID 33971902, 2021). "The c-MYC transcript levels were significantly higher in P#2T and P#13T organoid cultures (both cases had MSS tumor subtype and stage T3N0)." (PMID 34065672, 2021). "In MYC-induced murine renal carcinoma cells, the pharmacological inhibition of GLS1 by BPTES slowed tumor progression." (PMID 34503295, 2021). "It is also altered in GB and can bind directly to MYC protein, which is frequently amplified in G-CIMP+ tumours." (PMID 33432111, 2021). "The modulation of c-MYC gene expression, when treated with CisPt and/or RSV, was different in the two tumor cell lines." (PMID 34204834, 2021). "The authors noted increased influx of immune cells into the tumor and tumor regression upon oncogenic inactivation, and identified BRAF and MYC as key mediators of KRAS-induced immune evasion." (PMID 34957115, 2021). "Indeed, TA-mediated suppression of tumor cell viability is associated with multiple biochemical actions, including inhibition of protein synthesis, reduced activating phosphorylation of STAT3 and S6K1, decreased expression of the MYC oncoprotein, and suppression of Lys acetylation." (PMID 35095503, 2021). "The treated tumor showed several CNVs in driver genes, including amplifications in MCL1, TERT, CCND1, AKT1, MYC, EGFR, and FGFR3; deletions in CDK1B, CDKN2A and CDKN2B; a PIK3CA hotspot mutation; and a high TMB." (PMID 34680239, 2021). "Our analysis results showed that NAMPT has a high expression trend in the patients with a high MYC expression group, and compared with adjacent tissues, NAMPT has a significant upregulation trend in patient tumor tissues." (PMID 33540574, 2021). "In contrast, tumor EDCs from ESCC were found to be enriched in pathways that regulate endothelial cell development and cell fate (e.g., MYC related pathways and angiogenesis)." (PMID 34697289, 2021). "On the other hand, MYC is one of the downstream targets of the Wnt/β-catenin pathway, highlighting the dual potentiating role of CCAT2 in this tumor-promoting feedback loop." (PMID 34830370, 2021). "Four profiles were identified: ‘healthy (H) < tumour-adjacent (TA) < tumour (T), for CIN, GGI, MYC, proliferation and wound response; ‘H < TA = T’ for E2F3; ‘H = TA < T’ for 38-GES, 70-GES, glycolysis, IRGS and PNI; ‘H > TA > T’ for TGFβ." (PMID 33599248, 2021). "Loss of APC or GSK3 therefore activates Wnt target genes, such as MYC (c-Myc) and CCND1 (cyclin D1), and promotes tumor growth, as described in greater detail below." (PMID 33525562, 2021). "Nuclear MYC heterodimerizes with MAX and then binds to a specific DNA sequence (E-box) to regulate different biological activities of tumor cells, including cell proliferation, growth, metabolism and metastasis." (PMID 33572152, 2021). "Treatment with 10 μM CisPt resulted in a reduction of c-MYC gene expression in FaDu (p < 0.01, *) and less in PE/CA-PJ49 tumor cells compared to the control (untreated cells)." (PMID 34204834, 2021).
tumor (continued). "This explanation is consistent with previous data showing that the lncRNAs LINRIS and GLCC1 promote tumor growth by inhibiting the degradation and enhancing the stability of oncogenic proteins IGF2BP2 and c-MYC, respectively." (PMID 33668685, 2021). "Since ODC1 is an established MYC target gene, we investigated the possibility of differential effects of the SNP in subsets of patients depending on the MYCN status of their tumor." (PMID 33918978, 2021). "Using this method, we detected the upregulation of c-MYC and CXCR4 in both tumor and polyp, as well as downregulation of CD26 and Oct4 in tumor when comparing with normal plus polyp and polyp, respectively." (PMID 34335790, 2021). "Gene expression comparison between U-118 MG cells and the tumor showed an increased expression of neuronal and neural stemness genes MAP2, NEUN, ROBO2, PAX6, ZIC1, ZEB2, as well as MYC and OCT4 in tumor." (PMID 33468253, 2021). "And we show that disrupting the MYC–HCF-1 interaction promotes rapid and persistent tumor regression in vivo." (PMID 33416496, 2021). "Its inhibition has proven its therapeutic potential in a PDA mouse model driven by c-MYC (Ela1-c-MYC), reducing cell proliferation and tumor volume." (PMID 33669845, 2021). "We found that CYP7A1, GINS2, and PDLIM3 were significantly up-regulated, and MYC, MAMDC4, ADAMTS1, THBS1, and RASD1 were significantly down-regulated in HCC tumor samples compared to normal samples." (PMID 34777484, 2021). "It was found that the MYC expression level in patients with LUAD included in this study was positively correlated with the smoking history of patients, tumor stage (p = 0.028), and tumor diameter (p = 0.023)." (PMID 33540574, 2021). "We determined MAX, MGA, MYC, L3MBTL2, E2F6, and RNA polymerase II (RNA pol2, all phosphorylated forms) occupancy in Mga-inactivated and control (empty) KP tumor-derived cells lines." (PMID 34236315, 2021). "Mutation of these four HBM residues to alanine disrupts the interaction of MYC with HCF-1 in vitro and reduces the ability of MYC to promote murine fibroblast tumor growth in nude mice." (PMID 33416496, 2021). "Among MMRp CRCs, we found MYC and FLT3 amplification in one tumor (T32), MYC and CCND1 amplification in 1 tumor (T36), and EGFR amplification in one tumor (T38)." (PMID 33435234, 2021). "Previous studies have found that PP2A can inhibit the MYC gene and the AKT, KRAS, and NF-κB proteins, as well as other oncogenes and tumor signaling pathways, thereby exerting a tumor suppressor effect." (PMID 34485508, 2021). "Meanwhile, MYC-driven up-regulation of CD47, an antiphagocytic protein inhibiting the phagocytic effects of macrophages and DCs on tumor cells, on tumor cells can ultimately impair the potential of APCs to prime effector T cells." (PMID 34138315, 2021). "Since c-Myc is also a crucial regulator of many cellular processes in healthy cells, it is necessary to find ways for selective regulation of MYC expression in tumor cells." (PMID 34440124, 2021). "Collectively, the present study highlights the importance of DFMO treatment in suppressing MYC expression to improve treatment of chemo-resistant PDAC and the overall effectiveness of DFMO as a modulator of the PDAC tumor and immune microenvironment." (PMID 34947972, 2021). "The role of MYC in metabolic reprogramming of CRC was investigated in a study by Satoh and colleagues in which they compared multi-omics profiles across 275 matched tumour and normal patient tissues." (PMID 34445233, 2021). "Gene amplification (e.g., EGFR, TERT, MYC, and ERBB2) was identified in tumor samples from 10 patients but was present only in paired tumors for one patient." (PMID 34109114, 2021).